ARG1 (arginase 1)
Diseases named in the same sentence as ARG1 in open-access papers (continued):
Sharing a sentence is not in itself a finding about the gene and the disease.
melanoma (40 papers, 2014 to 2025). A malignant, usually aggressive tumor composed of atypical, neoplastic melanocytes. "Single-cell analysis showed that individual melanoma TAMs expressed different levels of multiple markers associated with M2-like states, like Arg1, CD206 and CD163, usually co-expressed, but also defining individual subsets." (PMID 34572807, 2021). "Moreover, the upregulation of arginase 1 (Arg1) in tumor-associated macrophages leads to polyamine synthesis, stimulating melanoma-initiating cell growth and contributing to an immunosuppressive microenvironment." (PMID 40573249, 2025). "However, we detected upregulated expression of Arginase 1 (Arg1) a marker associated with M2-like macrophages with immunosuppressive and pro-tumourigenic functions, in melanomas from Snail1ME-WT compared to Snail1ME-KO mice." (PMID 37516803, 2023). "Surprisingly, flow cytometry analysis showed that treatment of Flu in B16-F10 melanoma bearing mice significantly promoted the phenotype switch of neutrophils toward a N2 subtype (Arg-1+)." (PMID 40226609, 2025). "The results showed neutrophils expressed Arg-1 after cocultured with B16-F10 melanoma cells, and this trend was intensified while STAT1 was inhibited by Flu." (PMID 40226609, 2025). "Flow cytometry analysis confirmed a significant reduction in ARG1+ M2-like TAMs in the Smpd2 knockdown melanoma metastases." (PMID 41321310, 2025). "In preclinical models of melanoma, 2-DG decreases TAM expression of Arg1, Fizz, Mrc1 (encoding CD206), and Vegf, indicating that 2-DG diminishes immunosuppression within the TME." (PMID 38226622, 2024). "A very recent study on B16 melanoma metastasis showed that IL9 from CD4+ T cells exerted protumor functions by inducing the expression of Arg1, an M2 marker, in pulmonary interstitial macrophages." (PMID 36968220, 2023). "ARG1-specific IFNγ-producing Th1 CD4+ T cells were found in the mononuclear fraction of peripheral blood in patients with melanoma." (PMID 37185755, 2023). "Significantly higher levels of Ifng, Nos2, Il12, Ccl5, Cx3cl1, and Cxcl9 — and, by contrast, significantly lower levels of Arg1 — were detected in the melanomas of Colec11–/– mice, compared with WT mice." (PMID 36883567, 2023). "In our study, we observed that both Flu and adoptive transfer of N2-neutrophils led to a rise in N2-neutrophil (Arg-1+) levels in B16-F10 melanoma allografts when compared to the DMSO control group, which predominantly showed N1- neutrophil infiltration (iNOS)." (PMID 40226609, 2025). "Additionally, in an experiment applying temozolomide to treat melanoma mice, it was found that exocytic vesicles exfoliated by melanoma cells post-treatment polarize macrophages towards the M2 phenotype by upregulating M2-like genes such as ARG-1 and IL-10." (PMID 38787372, 2024). "CD8+ T cells from melanoma patients also showed an immune response against ARG1." (PMID 37185755, 2023). "Moreover, these EVs were able to favor melanoma re-growth in vivo, which was accompanied by an increase in Arginase 1 and IL10 gene expression levels by stromal cells and an increase in genes related to DNA repair, cell survival and stemness in tumor cells." (PMID 31597943, 2019). "In the B16 melanoma subcutaneous tumor model, CQ treatment consistently upregulated iNOS, while downregulating Arg1 in melanoma-infiltrating macrophages, concomitant with the increased expression of IFN-γ, IL-12p40, IL-12p35, and TNF-α, and downregulation of IL-10 in tumor tissues." (PMID 29491374, 2018). "Thus, the anti-oxidant action on the co-culture milieu was the principal cause for simultaneous suppression of key molecules involved in tumor progression in both cell types tested (reduction of HIF-1α levels in melanoma cells and ARG-1 levels in TAMs)." (PMID 30138430, 2018).
melanoma (continued). "In contrast to these reports, some evidence supports that melanoma cells with UPR activation could significantly up-regulate immunosuppressive Arginase 1 and PGE2 in DCs while simultaneously inhibit their capacity to cross-present antigens to CD8+T cells, which termed “transmissible ER stress”." (PMID 38291473, 2024). "Previously we also showed that TAMs stimulate tumor sphere formation from TICs in RETAAD melanomas by producing polyamines via the Arginase 1 pathway: this observation would suggest that polyamine metabolism might be dysregulated in these tumors as has been reported for other tumor cell types." (PMID 25762633, 2015). "It is the most enriched gene in the ARG1+ M2-like TAM cluster and was significantly reduced in TAMs following ZDHHC13 overexpression in melanomas." (PMID 41321310, 2025). "In the present study, we observed that melanoma promoted M2 macrophage polarization, as evidenced by increased expressions of CD206 and ARG1, as well as secretion of TGF-β." (PMID 39995996, 2025). "In the mitochondrial transplantation groups, Arg1 was upregulated not only in a tumor xenograft animal model, but also in a B16F10 melanoma cell model." (PMID 38339136, 2024). "It was found that the CNTFR silenced in melanoma cell lines increased the mRNA levels of INOS in THP-1 derived macrophages, whereas inhibited ARG1 expression." (PMID 36034849, 2022). "We compared their characteristics to the melanoma TAMs, evaluating the expression of CD11b, F4/80, Ly6C, CSF1R, iNOS, CD40, CD86, MHCII, Arg1, CD163 and CD206 expression by flow cytometry." (PMID 34572807, 2021). "Since CTX014 inhibits the accumulation of MDSCs as well as the expression of Arg1 and iNOS, both of which are known to suppress T-cell proliferation, on MDSCs, CTX014 induces melanoma-specific T cells to suppress tumor growth in the melanoma-bearing host." (PMID 32707850, 2020). "In addition, Arg1 was barely detected in B16F10 and ME276 cells with or without sorafenib, suggesting that Arg2 is the single isoform expressed in murine melanoma." (PMID 36604146, 2022). "A phase 1/2 clinical trial (NCT02903914) is currently testing the efficacy of the ARG-1 inhibitor INCB001158 (or CB-1158), as monotherapy and in combination with pembrolizumab, in patients with advanced/metastatic solid tumors, including melanoma." (PMID 33212945, 2020). "Targeting of effector functions can be achieved via inhibition of phosphodiesterase, reducing expression of Arg1 and iNOS, similar to the HDAC inhibitor entinostat, which reduces expression of COX2, Arg1, and NOS2 in mouse models of melanoma and renal carcinoma." (PMID 31849950, 2019). "Interestingly, ex vivo-differentiated B16-MDSCs were phenotypically equivalent to in vivo B16 melanoma intra-tumor MDSCs on representative markers, which included CD86, MHC II, CD62L, arginase-1 and PD-L1." (PMID 25151659, 2014). "In order to study the immediate impact of these N2-neutrophils on tumor progression in vivo, we conducted the transfer of N2-neutrophils (Ly-6G+Arg-1+), which were extracted from the bone marrow of healthy mice without tumors and then co-cultured with B16-F10 melanoma cells." (PMID 40226609, 2025). "Increased VEGF-C expression and LVD in TME of human melanoma show significant positive correlation with tumor-infiltrating CD8+ T cells and expression of immunosuppressive molecules, e.g., inducible nitric oxide synthase (iNOS), indoleamine 2,3-dioxygenase (IDO), and arginase-1 (ARG-1)." (PMID 41511312, 2025).
hepatocellular carcinoma (39 papers, 2012 to 2026). A malignant tumor that arises from hepatocytes. "Chang and co-workers recently reported that a conditioned medium of a mouse hepatoma cell line induced arginase-1 expression in BMDMs in association with a decrease of NF-κB p65." (PMID 27588757, 2016). "Hepatocellular carcinoma (HCC) is typically identified by markers such as arginase-1, GPC3, HepPar-1, and AFP, while cholangiocellular carcinoma (CCC) is positive for CK19 and CK8." (PMID 41515615, 2026). "In contrast, immunohistochemical staining for hepatocellular carcinoma would typically be positive for arginase 1, gpc3 hepatocytes, and AFP, and for cholangiocellular carcinoma, it would be positive for CK19 and CK8." (PMID 39099991, 2024). "A previous paper revealed that overexpression of ARG1 led to a significant increase in the expression of Vimentin, N-cadherin, and β-catenin both at protein and mRNA levels of hepatocellular carcinoma (HCC)." (PMID 36639644, 2023). "Our study built a new approach to monitor hepatocellular carcinoma models using an Arg1 luciferase reporter plasmid." (PMID 35251971, 2022). "Targeting HIF2α/AGR1 is considered as a novel treatment strategy for PAH, and Arg1 overexpression has been reported to be positively correlated with the viability and invasion ability of hepatocellular carcinoma cells." (PMID 35370672, 2022). "The extent to which arginase-1 expression is specific for hepatocellular carcinoma is still unclear, however." (PMID 34943588, 2021). "Because of its predominant expression in hepatocytes, it serves as a marker for hepatocellular carcinoma, although other tumor entities can also express arginase-1." (PMID 34943588, 2021). "This procedure is supported by more than 20 studies demonstrating arginase-1 expression in 80–100% of hepatocellular carcinomas." (PMID 34943588, 2021). "Of the 21 studies analyzing arginase-1 in hepatocellular carcinoma 9 described positivity rates of >90%." (PMID 34943588, 2021). "Among tumors, a nuclear and cytoplasmic arginase-1 immunostaining was predominantly observed in hepatocellular carcinoma, where 96% of 49 cancers were at least moderately positive." (PMID 34943588, 2021). "In summary, arginase-1 immunohistochemistry is highly sensitive and specific for hepatocellular carcinoma if weak and focal staining is disregarded." (PMID 34943588, 2021). "On the other hand, high expression levels of amino acid-degrading enzymes including IDO and arginase 1 have been associated with increased Treg infiltration in CRC, hepatocellular carcinoma (HCC) and uterine cervical cancer." (PMID 33532902, 2021). "In the article titled “The Oncogenic Role of ARG1 in Progression and Metastasis of Hepatocellular Carcinoma,” there was an error in the Acknowledgments section where the grant number 2016J0105 should be corrected to 2016J01529." (PMID 31911930, 2019). "In accordance with their physiological tissue distribution, expression of ARG1 by tumor cells is mainly limited to hepatocellular carcinoma, while ARG2, although largely understudied compared to ARG1, is found in the neoplastic cells of several human cancer types." (PMID 39211039, 2024). "Arg-1 is reported to be a highly specific biomarker for hepatocellular differentiation, with sensitivities of 100, 96.2 and 85.7% in highly differentiated, moderately differentiated and poorly differentiated hepatocellular carcinoma, respectively." (PMID 37575092, 2023). "The results have demonstrated that ARG1 may play a key role in the progression of hepatocellular carcinoma by promoting the EMT process." (PMID 35190747, 2022). "Additionally, Arginase-1 expression was commonly seen in hepatocellular carcinomas, maturing/keratinizing zones of squamous cell carcinomas and in tumor infiltrating granulocytes." (PMID 34943588, 2021).
hepatocellular carcinoma (continued). "The immunohistochemical markers of hepatocellular carcinoma include those of hepatocellular differentiation—such as hepatocyte paraffin 1 and arginase-1—and those of malignant hepatocytes—such as glypican-3, heat shock protein 70, and glutamine synthetase (GS)." (PMID 34071338, 2021). "They assumed that care should be taken when using arginase-1 as a hepatocyte marker for distinguishing between a poorly differentiated hepatocellular carcinoma and a mass-forming peripheral intrahepatic CC showing the histology of poorly differentiated adenocarcinoma." (PMID 23111165, 2012). "Arginase 1 and FGL-1 levels were extremely elevated in hepatocellular carcinoma, as they are in healthy liver tissues." (PMID 40788962, 2025). "Hepatocellular carcinoma (HCC) is typically immunopositive for HepPar1 and Arginase-1 and shows canalicular immunopositivity for CD10 and bile salt exporter protein." (PMID 38699072, 2024). "The expression of hepatocellular carcinoma markers, including AFP, Arginase-1, Glypican-3 (GPC-3), SALL4, and Hep-1, provides valuable insights into the correlation with hepatocytes." (PMID 37950062, 2023). "Arg-1 and GPC-3 have been extensively used to differentiate hepatocellular carcinoma cells from cholangiocarcinoma and metastatic tumor cells in the liver because of their sensitivity." (PMID 34715880, 2021). "Nevertheless, the concrete role and clinical significance of ARG1 in the progression of hepatocellular carcinoma (HCC) remain unclear." (PMID 30320132, 2018). "NO, Arg-1 and SCOS3 were induced in hepatoma-treated TLR2−/− BMDM." (PMID 37925462, 2023). "Subsequently, we found that after culturing macrophages using conditioned medium from hepatocellular carcinoma cells with knockdown of SLC1A5, the expression of M2-type macrophage marker molecules was decreased, and the expression levels of CD206 and ARG1 were markedly down-regulated in macrophages." (PMID 37818360, 2023). "All tumors were negative for Hep-Par1 and Arg-1 (specific markers for hepatocellular carcinoma) expression." (PMID 35347134, 2022). "Most of the previous studies agree that the few arginase-1 negative hepatocellular carcinomas are often poorly differentiated." (PMID 34943588, 2021). "For example, ARG1, CYP2C8, CYP3A4, CYP3A7 and CYP4A11, which we identified using MOG as decreasing expression with LIHC progression, have each been recently studied as prognostic markers for hepatocellular carcinoma." (PMID 31956905, 2020). "Therefore, from the findings of the current and previous few studies about arginase-1 immunostaining in HCC, we can expect that it will be used as a hepatoma marker in routine surgical pathology practice." (PMID 23111165, 2012). "Nevertheless, our study showed absence of HepPar 1 and Arginase-1 in all of the UESL cases highlighting the importance of this maker in differentiating UESL from hepatocellular carcinoma for which these two markers have been shown to display a sensitivity of 84.4 and 96.0%, respectively." (PMID 34162402, 2021). "Arginase-1 has been reported as an indicator of poor prognosis in CRC and a marker of non-malignant hepatocytes and hepatocellular carcinoma; therefore, it was assayed in liver metastasis." (PMID 38612832, 2024). "Moreover, treatment of hepatocellular carcinoma (HCC)-bearing mice with IFN-α shifted TAM phenotypes from an M2-like to an inflammatory polarization, characterized by decreased expression of CD206 and arginase 1 (Arg1) and increased expression of inducible nitric oxide synthase (iNOS)." (PMID 40098954, 2025).
COVID-19 (37 papers, 2020 to 2025). A disease caused by infection with severe acute respiratory syndrome coronavirus 2. "Phenotypically, neutrophils from patients with COVID-19 displayed features associated with cellular activation, increased arginase-1 expression, and an increase in neutrophil subpopulations with immature and aged phenotypes." (PMID 39253969, 2024). "A recent study reported that dexamethasone treatment in patients with COVID-19 is associated with the appearance of neutrophil populations with increased ARG1 gene expression." (PMID 39253969, 2024). "Monocytic MDSC growth is strikingly associated with COVID-19 disease severity and purified MDSCs block T cell proliferation, in part, via an ARG1-dependent mechanism, supporting a role for these cells in the aberrant COVID-19 immune response." (PMID 35323682, 2022). "Myeloid-driven immune suppression is a hallmark of COVID-19 evolution, highlighting arginase-1 expression with immune regulatory features of monocytes." (PMID 33674591, 2021). "The ROC analysis showed a significant diagnostic value for Arg1 expression in COVID-19 samples compared to control samples (p = 0.0002, and AUC = 0.8401)." (PMID 33806290, 2021). "In contrast, G-MDSC from severe COVID-19 patients had increased expression of genes associated with granulocyte functions/degranulation and chronic inflammation including Arg1, MMP8, MMP9, S100A8 and A9, MPO, IL18RA, elastase, PRTN3 (azurophilic granule protein 7)." (PMID 34341659, 2021). "Arg1 up-regulation might be associated with a higher virus load in COVID-19 patients." (PMID 36635345, 2023). "In addition, ARG1 is upregulated in whole blood, plasma, and peripheral blood mononuclear cells of patients with COVID-19 and may be a valuable diagnostic marker of the disease." (PMID 35323682, 2022). "Moreover, the ROC analysis highlights Arg1 expression as a valuable diagnostic marker for COVID-19." (PMID 33806290, 2021). "Moreover, we have proposed that Arg1 up-regulation might be associated with higher virus load in COVID-19 patients." (PMID 33806290, 2021). "We further characterized macrophage M2-type polarization in COVID-19 patients by measuring the expression levels of IL-10, Arg-1, TGF-β, and VEGF in plasma." (PMID 40160824, 2025). "We found that whole blood (WB) neutrophils obtained from a single patient with mild and a single patient with severe COVID-19 showed altered arginase-1 distribution in mild and severe COVID-19." (PMID 39253969, 2024). "To explore why neutrophils in patients with COVID-19 cannot release arginase-1 despite evidence of greater intracellular arginase-1 expression, we assessed the intracellular localization of this enzyme using imaging flow cytometry." (PMID 39253969, 2024). "Neutrophils from patients with severe COVID-19 had increased expression of arginase-1 protein, a feature that was retained in convalescent patients." (PMID 39253969, 2024). "Investigating this further, we found that serum arginase-1 concentrations were actually lower in both mild and severe COVID-19." (PMID 39253969, 2024). "Given the alteration in neutrophil function in COVID-19, we next investigated the impact on processing and release of arginase-1, a neutrophil-derived modulator of T cell function." (PMID 39253969, 2024). "Neutrophil arginase-1 expression remains elevated throughout the COVID-19 disease course through to convalescence." (PMID 39253969, 2024). "We observed distinct populations of arginase-1–positive neutrophils from acute and, most notably, in convalescent COVID-19 patients, which were also CD16loCD10intCD62Lint." (PMID 39253969, 2024). "In neutrophils from a single healthy control, arginase-1 staining was localized in discrete granules, whereas in the mild COVID-19 case there was diffused cytoplasmic staining." (PMID 39253969, 2024).